TMEM252 (transmembrane protein 252)
Synonyms: C9orf71; MGC34760
Tractability: Antibody: UniProt predicts a signal peptide or a membrane-spanning region; the Human Protein Atlas places it where antibodies can reach.
Gene: Protein-coding gene on chromosome 9 (68,536,580 to 68,540,883, reverse strand). Ensembl gene ENSG00000181778.
Subcellular location: Membrane
Subcellular location (Human Protein Atlas): Nuclear speckles; Plasma membrane; Basal body; Primary cilium
Gene Ontology:
Molecular function: protein binding
Cellular component: membrane
Genetic constraint (gnomAD): Loss-of-function variants: 6 observed, 8.69 expected, observed/expected ratio (o/e) 0.69, 90% interval 0.38 to 1.36. That is too few expected variants to judge how well the gene tolerates losing a copy. Missense variants: 207 observed, 215.93 expected, observed/expected ratio (o/e) 0.96, 90% interval 0.86 to 1.08. Synonymous variants: 85 observed, 86.28 expected, observed/expected ratio (o/e) 0.99, 90% interval 0.83 to 1.18.
Homologues: Orthologues: chimpanzee TMEM252 (99% identical), macaque TMEM252 (93% identical), dog TMEM252 (73% identical), pig TMEM252 (70% identical), mouse Tmem252 (65% identical), guinea pig TMEM252 (64% identical), rat Tmem252 (63% identical), tropical clawed frog tmem252 (38% identical).
Diseases named in the same sentence as TMEM252 in open-access papers:
TMEM252 is named in the same sentence as 9 diseases in open-access papers, as found by Europe PMC text mining. Sharing a sentence is not in itself a finding about the gene and the disease. The quoted sentences say what the papers report.
diabetes (2 papers, 2016 to 2022). "Among these diabetes-induced DEGs, 14 up-regulated DEGs and 21 down-regulated DEGs were completely restored by Sal treatment, and only one DEGs (Tmem252) was aggravated after Sal intervention." (PMID 35370972, 2022). "Treatment also completely reversed diabetes-induced expression changes of Mamdc4, Kdm4b, Tmem252, Selm, and Hpd while others were returned in the direction of normal levels from their diabetes-induced state by ~50%." (PMID 27855634, 2016). "Expression of other coding genes regulated by diabetes with FC > =(+/-) 1.5 and completely reversed by P78 include Mamdc4, Kdm4b, Tmem252, Selm, and Hpd." (PMID 27855634, 2016).
Cachexia (1 paper, 2022). Severe weight loss, wasting of muscle, loss of appetite, and general debility related to a chronic disease. "First, we found that Lcn2 KO mice had more moderate cachexia and correspondingly decreased induction of a subset of the DE genes found in our scRNAseq model, such as Plin4, Tmem252, and Ly6a." (PMID 35031523, 2022).
COVID-19 (1 paper, 2023). A disease caused by infection with severe acute respiratory syndrome coronavirus 2. "The results revealed that 6 key gene signatures (RRM2, EGF, TMEM252, RARRES1, COL6A3, CUBN) were recognized to have great influences on COVID-19 and AKI." (PMID 37789254, 2023). "We successfully identified the shared 6 candidate gene signatures (RRM2, EGF, TMEM252, RARRES1, COL6A3, CUBN) between COVID-19 and AKI." (PMID 37789254, 2023).
diabetic nephropathy (1 paper, 2019). "In another study, using RNA-seq to identify diabetic nephropathy, the expression of TMEM252, increased in diabetic patients relative to wild-type controls, but we have not found any relevant studies of TMEM252 in tumours." (PMID 31297036, 2019).
squamous carcinomas (1 paper, 2025). "Among the most significantly downregulated transcripts in later stage tumors are DEFB132 (a defensin involved in innate immunity), C14orf180 (an integral plasma membrane protein), TMEM252 (an integral plasma membrane protein), and LINC01537, an LncRNA associated with squamous carcinomas." (PMID 41224793, 2025).
tumour (3 papers, 2019 to 2025). "Interestingly, four out of five REs consistently down-regulated in all 12 cancer types were located in the intronic region of the TMEM252, a recently discovered tumor suppressor gene." (PMID 40428352, 2025).
cancer (2 papers, 2023 to 2025). A tumor composed of atypical neoplastic, often pleomorphic cells that invade other tissues. "TMEM252 expression was also down-regulated in 10 of 12 cancer types, suggesting its potential importance across a wide range of cancer types." (PMID 40428352, 2025). "Notably, four of the five down-regulated REs were located within the intronic region of the TMEM252 gene, which itself was down-regulated in ten out of twelve cancer types." (PMID 40428352, 2025).
TMEM252 also shares sentences with these, for which no sentence is quoted: amyotrophic lateral sclerosis (1 paper); Parkinson disease (1).